THAP5 (THAP domain containing 5)
Description:
Has sequence-specific DNA-binding activity and can function as transcriptional repressor (in vitro). May be a regulator of cell cycle: THAP5 overexpression in human cell lines causes cell cycle arrest at G2/M phase.
Synonyms: DKFZp313O1132
Tractability: PROTAC: ubiquitination databases record sites on it.
Gene: Protein-coding gene on chromosome 7 (108,554,543 to 108,569,750, reverse strand). Ensembl gene ENSG00000177683.
Subcellular location: Nucleus
Subcellular location (Human Protein Atlas): Nucleoplasm
Gene Ontology:
Molecular function: protease binding
Biological process: negative regulation of cell cycle; negative regulation of transcription by RNA polymerase II
Cellular component: chromatin; nucleoplasm; nucleus
Genetic constraint (gnomAD): Loss-of-function variants: 28 observed, 35.25 expected, observed/expected ratio (o/e) 0.79, 90% interval 0.59 to 1.09. The upper end of that interval is the gene's LOEUF score, 1.09, which puts it in group 4 of 6, group 1 being the genes least tolerant of losing a copy. Missense variants: 394 observed, 457.95 expected, observed/expected ratio (o/e) 0.86, 90% interval 0.79 to 0.94. Synonymous variants: 125 observed, 156.15 expected, observed/expected ratio (o/e) 0.8, 90% interval 0.69 to 0.93.
Homologues: Orthologues: chimpanzee THAP5 (99% identical), macaque THAP5 (96% identical), dog THAP5 (86% identical), rabbit THAP5 (83% identical), guinea pig THAP5 (83% identical), pig THAP5 (82% identical).
Diseases named in the same sentence as THAP5 in open-access papers:
THAP5 is named in the same sentence as 4 diseases in open-access papers, as found by Europe PMC text mining. Sharing a sentence is not in itself a finding about the gene and the disease. The quoted sentences say what the papers report.
breast carcinoma (1 paper, 2022). "THAP1 has been associated with DYT6 dystonia, THAP5 and THAP1 have been linked to apoptosis, the LRRC49/THAP10 bidirectional gene pair is involved in breast cancer, and THAP11 has been implicated in colon and gastric cancers." (PMID 35893234, 2022).
heart diseases (1 paper, 2020). "THAP5 is a cell cycle inhibitor and closely related to certain heart diseases." (PMID 32908912, 2020).
tumor (1 paper, 2013). "ANKRD40, HNRNPF, IQGAP2, OTUD7B, and THAP5 mutations were detected in 1 tumor, each." (PMID 24223926, 2013).
THAP5 also shares sentences with these, for which no sentence is quoted: gastric cancer (1 paper).